SNORD13P3 (small nucleolar RNA, C/D box 13 pseudogene 3)
Synonyms: U13; U13.4B; RNU13P3
Gene: Small nucleolar RNA gene on chromosome 3 (47,250,523 to 47,250,626, reverse strand). Ensembl gene ENSG00000239128.
Homologues: Orthologues: chimpanzee SNORD13P3 (95% identical). Paralogues in human: SNORD13 (95% identical), SNORD13E (87% identical), SNORD13P1 (86% identical), SNORD13D (85% identical).